USP22 (ubiquitin specific peptidase 22)
Diseases named in the same sentence as USP22 in open-access papers (continued):
Sharing a sentence is not in itself a finding about the gene and the disease.
metastatic melanoma (1 paper, 2011). A melanoma that has spread from its primary site to another anatomic site. "The expression of three out of four analyzed genes (USP10, USP11, USP22) was significantly higher in metastatic melanoma compared with benign nevi and primitive tumors, suggesting that their expression is associated with a more aggressive and invasive phenotype." (PMID 21283576, 2011).
Obesity (1 paper, 2024). Accumulation of substantial excess body fat. "Several USPs, including USP2, USP10, USP14, USP15, USP18, and USP22, have been associated with obesity and related metabolic disorders." (PMID 38322269, 2024). "Furthermore, USP22 reduces hepatic steatosis and obesity by stabilizing Sirt1 protein and regulating Sirt1-dependent mitochondrial respiration." (PMID 38322269, 2024).
papillary carcinoma (1 paper, 2015). A malignant epithelial neoplasm characterized by a papillary growth pattern. "Kaplan–Meier analysis indicated that the survival of patients with papillary carcinoma was significantly lower with high USP22 expression levels." (PMID 25605410, 2015). "USP22 is overexpressed in papillary carcinoma, a type of thyroid cancer." (PMID 25605410, 2015). "Taken together, the authors concluded that USP22 could be functioning as an oncogene and used in the prognosis of papillary carcinoma." (PMID 25605410, 2015). "USP22 expression is increased in laryngeal squamous cell carcinoma, salivary adenoid cystic carcinoma, cervical cancer, salivary duct carcinoma, colorectal carcinoma, breast cancer, oral squamous cell carcinoma, and papillary carcinoma." (PMID 25605410, 2015). "Increased USP22 protein levels were shown for papillary carcinoma tissue when compared with noncancerous tissue using immunohistochemistry." (PMID 25605410, 2015).
pharyngeal squamous cell carcinoma (1 paper, 2022). A squamous cell carcinoma that arises from the pharynx. "In pharyngeal squamous cell carcinoma, USP22 expression is up-regulated while knockdown of USP22 expression increases the expression level of cyclin P21 and P27, but reduced the level of phosphorylated RB protein, thereby inhibiting the growth and proliferation of Fa Du cells." (PMID 35356205, 2022).
spinocerebellar ataxia 7 (1 paper, 2021). "A distant and indirect member of the DUB family associated with NDD phenotypes is USP22 which participates in the pathogenesis of spinocerebellar ataxia 7 caused by poly Q repeats in the ATX7 gene." (PMID 34566579, 2021).
steatosis (1 paper, 2022). Increased lipid within the cytoplasm of cells. "Further analysis also revealed that the increased expression of USP22, PPARγ, ACC and ACLY were associated with steatosis in the HCC TMAs." (PMID 35449157, 2022).
thyroid (1 paper, 2016). "To further evaluate the association of USP22 with ATC malignancies, we analyzed USP22 levels in ATC cell lines (CAL-62 and 8505C) and one benign human thyroid follicular cell line (Nthy-ori 3-1)." (PMID 27145278, 2016).
cancer (144 papers, 2011 to 2026). A tumor composed of atypical neoplastic, often pleomorphic cells that invade other tissues. "According to the study, elevated USP22 expression was linked to a worse chance of survival and a lower OS rate in several types of cancer." (PMID 42129581, 2026). "Ubiquitin specific protease 22 (USP22) is considered an oncogene that is commonly upregulated in various malignant tumors and is associated with their poor prognosis." (PMID 41541703, 2026). "USP22 regulates key signaling pathways associated with cancer development and progression in NSCLC, such as the Wnt/β-catenin and PI3K/Akt pathways." (PMID 40075700, 2025). "The regulation of SIRT1 based on NAD+/NADH ratio is also seen in other molecules, Ubiquitin specific protease 22 (USP22) is a deubiquitinase that is believed to be associated with various cancers." (PMID 40567502, 2025). "USP22 is highly expressed in several cancer types and USP22 abundance is linked to disease severity by promoting oncogenic gene expression, aberrant cell cycle regulation and cancer cell proliferation." (PMID 38467608, 2024). "Studies across various cancer types have consistently shown that high USP22 expression is associated with enhanced cancer cell survival, immune evasion, and poor prognosis." (PMID 38474186, 2024). "USP22 is a heavily studied DUB in cancer research due to its reported association with several aggressive features in many cancer entities." (PMID 38347585, 2024). "USP22 was initially characterized as a member of an 11-gene "death-from-cancer" signature that strongly associated with a poor response to standard therapies and an overall decreased patient survival." (PMID 38347585, 2024). "Studies show USP22 is abnormally expressed in many tumor diseases and closely associated with cancer initiation, progression and prognosis." (PMID 38784391, 2024). "The role of USP22 overexpression in tumorigenesis and metastasis is an important question, as it is associated with highly aggressive, therapy resistant cancers." (PMID 38236941, 2024). "Here, we investigate the functional interplay of the cancer-associated DUB USP22 with the master cell fate regulatory protein PML to gain deeper insights in the pro-tumorigenic functions of USP22." (PMID 38467608, 2024). "Ubiquitin-specific processing peptidase 22 (USP22) is reported to be highly expressed and associated with tumor malignancy and prognosis in cancers." (PMID 38784391, 2024). "Overexpression of ubiquitin specific protease 7 and 22 (USP7 and USP22) are associated with malignancy, therapy resistance, and poor prognosis in many cancers." (PMID 37946202, 2023). "USP22 was initially identified as one component of a “Death-By-Cancer” 11-gene mRNA signature associated with poor prognosis in a variety of cancers." (PMID 37946202, 2023). "Second, we also examined the impact of USP7 inhibition through upregulation of USP22 on H2Bub1, which is a well-known and key target of USP22 in cells and is associated with more malignant phenotype and poor prognosis of various cancers." (PMID 37946202, 2023). "USP22 is part of the Spt-Ada-GCN5-acetyltransferase (SAGA) complex that is linked to cancer progression." (PMID 35008940, 2022). "Overall, this study highlighted the associations between hypoxia, cancer stemness, and metabolism and also provided a mechanism by which HIF1α/USP22 promote glycolysis and stemness in HCC." (PMID 36497394, 2022). "Upregulated USP22 develops resistance to conventional therapy and increases the risk of cancer cell metastasis, resulting in patient death." (PMID 35935969, 2022). "USP22 is upregulated in different cancer types and is associated with poor prognosis in numerous malignancies." (PMID 35008940, 2022). "Intriguingly, inactivation of ubiquitin-specific protease 22 (USP22), member of gene expression signature known as “death-from-cancer”, associates with lower HSP90β expression in mammary and colorectal cell lines." (PMID 35127545, 2022).
cancer (continued). "TSA also suppressed the expression of the ubiquitin-specific protease 22 (USP22), a gene overexpressed in most cancer cells and implicated in tumorigenesis." (PMID 36297347, 2022). "In cancer, USP22 was initially identified as one component of a “Death-By-Cancer” 11-gene signature associated with poor prognosis in a variety of cancers." (PMID 36123698, 2022). "In agreement with USP22 depletion being a pathogenic event in cancer, we determined that USP22 deletions occur frequently in many cancer types and shallow/deep deletions are associated with worse progression-free survival." (PMID 33801331, 2021). "Loss of USP22 expression has also been shown to increase apoptosis in several cancer cell lines, including the colorectal cell line HCT116." (PMID 33369872, 2021). "Ubiquitin-specific protease (USP22) promotes stability of multiple cancer-associated protein targets through deubiquitylation (e.g., TRF1 and SIRT1), and influences oncogene accumulation." (PMID 34070986, 2021). "Higher expression of USP22 is associated with increased risk of cancer recurrence and poor disease-free survival." (PMID 34660907, 2020). "USP22 has been associated with increased angiogenesis, cancer cell proliferation and metastasis, cisplatin and irradiation resistance and DNA damage signalling." (PMID 33233707, 2020). "As a member of the 11-gene “death-from-cancer” gene expression signature, overexpression of the Ubiquitin-Specific Protease 22 (USP22) was associated with poor prognosis in various human malignancies." (PMID 31801945, 2019). "Several studies have shown that USP22 plays a key role in tumorigenesis and is a potential diagnostic and prognostic marker of human cancers." (PMID 31689236, 2019). "Remarkably, USP22 knockout had pronounced effects on expression of these important cancer-associated gene sets such as c-Myc, E2F, and selected genes including ALDH1A3, CCNE1/G1, E2F6, HOXA1, MMP9, NFKB2, TP63, TPM4, SET7/9 were validated by qRT–PCR." (PMID 31842906, 2019). "Statistical analysis showed that the intensities of USP22 immunostainings were positively associated with cancer recurrence (P = 0.044) and a trend toward advanced stage (P = 0.088) in these NSCLC tissues." (PMID 31842906, 2019). "A study by digging The Cancer Genome Atlas (TCGA) data found that USP22 gene is much more frequently lost (homozygous or heterozygous loss) than gained in many cancer types." (PMID 31842906, 2019). "Up-regulation of USP22 expression is associated with the development and progressionof several types of cancers and leads to abnormal activation of multiple pathwaysthat support cell survival (Schrecengost etal., 2014)." (PMID 30088609, 2018). "Recently, USP22 over-expression isfound in several types of cancers and associated with the recurrence, metastasis andpoor survival of patients with cancers (Piaoet al., 2012; Tanget al., 2015)." (PMID 30088609, 2018). "For instance, H2A ubiquitin ligase RNF2/RING1b and H2B deubiquitinase USP22 are associated with poor prognosis in numerous cancers." (PMID 29934362, 2018). "While homozygous deletion of USP22 occurs in 0–4% of most cancers, shallow deletions (i.e., heterozygous loss) are the most prevalent forms of copy number alterations." (PMID 29210986, 2017). "At the gene level, data from The Cancer Genome Atlas (TCGA) indicate that in many cancer types, USP22 is more frequently lost (homozygous or heterozygous loss) than gained." (PMID 29210986, 2017). "Over 80 distinct non-synonymous USP22 mutations have been reported in multiple cancer types in TCGA." (PMID 29210986, 2017). "Frequent overexpression of USP22 has been observed in various cancer types and is associated with poor patient prognosis." (PMID 29210986, 2017). "Whole-exome sequencing studies show that non-synonymous USP22 mutations typically occur in 1–4% of any given cancer type." (PMID 29210986, 2017).
cancer (continued). "Altered USP22 expression is also linked to an additional cancer hallmark, namely the alteration of cell cycle progression and checkpoints." (PMID 29210986, 2017). "Although USP22 was reported as a “death-from-cancer” signature and was aberrantly increased in many cancers, the molecular mechanisms underlying the elevated expression of USP22 during GC progression and poor prognosis are still elusive." (PMID 28415621, 2017). "USP22 has been linked to poor prognosis in cancer, making it a very attractive target in cancer research." (PMID 27516771, 2016). "Aberrant expression of the Ubiquitin-Specific Peptidase 22 (USP22) has been associated with poor cancer prognosis and neurological disorders." (PMID 27057639, 2016). "USP22 is emerging as a potential oncogene linked not only to resistance and metastasis in different types of cancer." (PMID 27057639, 2016). "Elevated USP22 protein levels are associated with advanced tumor stage and poor prognosis in several cancer types." (PMID 27145278, 2016). "Since then USP22 has been reported to stabilize some cancer-associated proteins and increased expression was correlated to poor prognosis." (PMID 26431380, 2015). "USP22 is highly expressed in cancer tissues and is significantly associated with progression and unfavorable clinical outcome." (PMID 24466336, 2014). "USP22 is a cancer-related protein, controls a large variety of genes and, as such, is associated with deregulating signaling altered in cancer and suggested as a potential novel target for cancer drugs." (PMID 25547493, 2014). "More importantly, USP22 is considered as one of the putative cancer stem cell markers, and changes in the expression of USP22 have been linked with metastatic potential and therapeutic outcome in human cancer." (PMID 23300749, 2012). "USP22 has been speculated to act as a critical cancer stem cell gene 17, however, the molecular pathways underlying if and how USP22 maintain cancer cell stemness and control CSC self-renewal remain to be fully defined." (PMID 37398311, 2023). "This inconsistency may be caused by different cancer cells used in each study and or experimental variations, since we found that the dynamic changes in USP22 mRNA occurred quickly, but lasted only a short time after stimulation or modulation." (PMID 36123698, 2022). "Ubiquitin-specific protease 22 (USP22) was identified as a member of the so-called 11-gene “death-from-cancer” expression signature which was associated with distant metastasis, high recurrence rates and poor patient survival in several cancer entities, including CRC." (PMID 33920268, 2021). "Expression of USP22 has been associated with stemness in cancer." (PMID 33233707, 2020). "Since USP22 knockout significantly decreased the capacity of NHEJ, a major pathway for DNA DSBs repair, we further investigated whether USP22−/− cancer cells are more sensitive to irradiation that causes DSBs for cancer treatment." (PMID 31842906, 2019). "USP22 is positively associated with metastasis of several cancers." (PMID 31689236, 2019). "In this study, we assessed the status, biological significance and therapeutic implications of USP22, and explored the mechanism by which USP22 may affect cancer-associated signaling pathways in NSCLC cells." (PMID 31842906, 2019). "Ourdata may provide new insights into the role of USP22 in regulating the expression ofgenes associated with cancer progression." (PMID 30088609, 2018). "In addition, as a crucial subtype of human Spt-Ada-Gcn5 acetyltransferase (hSAGA), USP22 promotes the stability of multiple cancer-associated protein targets through deubiquitylation and influences oncogene accumulation." (PMID 28445968, 2017).
cancer (continued). "Clarifying the impact aberrant USP22 expression and abnormal H2Bub1 levels have in oncogenesis is critical before precision medicine therapies can be developed that either directly target USP22 overexpression or exploit the loss of USP22 expression in cancer cells." (PMID 29210986, 2017). "Altered USP22 expression was first implicated in cancer in 2005 when its upregulation was identified as part of an 11-gene expression signature, termed “death-from-cancer”, that defined primary tumors with stem cell-like expression profiles." (PMID 29210986, 2017). "USP22 plays important roles in many cancers; however, its effect and the mechanism underlying HCC chemoresistance remain unclear." (PMID 28445968, 2017). "Increasing evidences showed that USP22 serves a critical function in numerous pathological progresses and may be used as a highly promising diagnostic and/or prognostic marker of cancers." (PMID 27145278, 2016). "Although the frequency of USP22 somatic mutations reported is very low (<0.5%), multiple reports show that USP22 is highly expressed at the mRNA and protein level in several types of cancer." (PMID 27057639, 2016). "Interestingly, USP22 deletions are associated with reduced survival in several cancer types, suggesting that reduced expression/function may also contribute to cancer initiation and progression." (PMID 33801331, 2021). "Hence, accurate regulation of USP22 expression and function, and by extension H2Bub1 abundance, appears critical as both hypermorphic and hypomorphic USP22 activity are associated with aberrant phenotypes known to promote cancer progression." (PMID 29210986, 2017). "Interestingly, human USP22 has been linked to suppression of cell proliferation in cancer." (PMID 25779050, 2015). "Thus, we proposed that USP22 activation may be implicated in the initiation and progression of cancer." (PMID 22880026, 2012). "As a member of an 11‐gene ‘death‐from‐cancer’ signature, USP22's non‐histone substrates play a critical role in mediating its pro‐oncogenic function." (PMID 40341781, 2025). "Coculture of CD8+ OT-I T cells with either Usp22 KO MC38 or RM1 cancer cells with stable OVA expression enhanced CD8+ T cell activation, indicated by elevated CD69 expression and tumor cell killing." (PMID 41252204, 2025). "Collectively, our results indicate that USP22 is a de novo deubiquitinase of the MHC-I suppressor EZH2 in cancer cells." (PMID 41252204, 2025). "USP22 also promotes chemotherapy resistance by inhibiting Bax-mediated apoptosis and is reportedly a critical cancer stem cell gene." (PMID 41252204, 2025). "Analysis of human cancer tissues revealed a positive correlation of USP22 with EZH2, both of which were negatively correlated with MHC-I expression and intratumoral CD8+ T cell infiltration." (PMID 41252204, 2025). "Future studies with larger cohorts and across additional cancer types will be necessary to establish USP22 expression as a reliable biomarker for predicting ICB therapy responsiveness." (PMID 41252204, 2025). "In conclusion, our research elucidates the mechanism of MYH9 and the p-MYH9 /USP22/HIF-1α axis in promoting cancer stemness and LR in HCC." (PMID 39300073, 2024). "To confirm the USP22-dependent OXPHOS-transcriptomic program in these cancer entities, we performed quantitative real-time PCR (qRT-PCR)." (PMID 38347585, 2024). "All of these potent USP22 inhibitors have demonstrated respectable antitumor activities in preclinical research, underscoring the clinical value of USP22 in cancer treatment." (PMID 39135915, 2024). "For instance, USP22 can enhance the deubiquitination and stabilization of PD‐L1 in cancer cells, suggesting its protumorigenic role in cancer." (PMID 39143031, 2024). "In order to better define USP22 functions in cancer, we created mouse models to determine its functions during normal development." (PMID 38236941, 2024).